KIT (KIT proto-oncogene, receptor tyrosine kinase)
Diseases named in the same sentence as KIT in open-access papers (continued):
Sharing a sentence is not in itself a finding about the gene and the disease.
cancer (continued). "According to the prediction and molecular docking results presented in this study, erianin shows high potential to interact with molecules like PIK3CA, RET, KIT, ABL1, and FLT3 in cancers, all of which were found to play important roles in cancer progression." (PMID 35372513, 2022). "A third inhibitor, ripretinib (DCC-2618), was designed to inhibit the full spectrum of mutant KIT and PDGFRA kinases in cancers." (PMID 35050442, 2022). "Additional amplifications were found in other cancer-related genes including ARAF, SF3B1 in CTCs and KIT in cfDNA." (PMID 35269713, 2022). "Customized probes were designed to capture exonic regions of 141 genes selected for the panel, which was aimed for the detection of clinically actionable genetic variations in cancer, including KRAS, NRAS, BRAF, ALK, ROS1, KIT and EGFR." (PMID 35446881, 2022). "Several studies conducted on HGSOC have demonstrated that cancer stem-like cells (CSC) are characterized by a set of markers such as ALDH1, CD44, CD117(c-KIT), and CD1332,3." (PMID 33828085, 2021). "Rituximab used for treatment of various cancers was repurposed for Rheumatoid arthritis and use of imatinib for therapy of BCR-ABL-positive cancers was expanded to c-KIT gastrointestinal cancers." (PMID 33669809, 2021). "Lenvatinib also inhibits PDGFR alpha, stem cell factor receptor (KIT), and RET, receptor tyrosine kinases that have been reported to be involved in cancer progression." (PMID 34176067, 2021). "Other markers, including placental-like alkaline phosphatase (PLAP), the stem cell factor receptor KIT, and TFAP2C (AP2γ) also provide evidence that GCNIS and its derived cancers are similar to PGCs." (PMID 33805941, 2021). "For patient ID 110, this notably included MAP2K2, KIT, VEGFA, A2M, ICAM1 and PLA2G4A, all of which are involved in cancer development." (PMID 34771574, 2021). "Imatinib is a tyrosine kinase inhibitor with activity against BCR-ABL, c-KIT, and PDGFR-α and -β with applications in cancers." (PMID 33591958, 2021). "For example nocodazol, a colchicine binding site agent was found to simultaneously inhibit various cancer-related kinases, including ABL1, c-KIT, BRAF, MEK1 (MAP2K1), MEK2 (MAP2K2), and MET." (PMID 33671106, 2021). "Many papers elucidated other pathways like expression of KIT (CD117) ligand and CXCR2 receptors by cancer cells enhance response to hypoxia, which disturb neutrophils retention in bone marrow." (PMID 32970873, 2021). "In accordance with this result, BMP2 increased the expressions of mRNA for the cancer stem cell markers CD44 and c-KIT." (PMID 34360647, 2021). "For example, targeting the PI3k-Akt signaling pathway results in an anti-leukemic effect by activating oncogenes upstream (FLT3-ITD, KIT, NRAS, etc.); and dysregulated Ca2+ homeostasis plays a crucial role in the pathogenesis of various cancers." (PMID 33926391, 2021). "For example, in urologic cancer, common genes regulated by prognosis-alternative miRNAs such as BCL2, EGFR, KIT, PDGFRA, and VEGFA, have been validated as anti-cancer drug targets previously." (PMID 32523951, 2020). "AKT3, KIT proto-oncogene, receptor tyrosine kinase (KIT) and retinoic acid receptor beta (RARB) were also involved in pathways in cancer." (PMID 33176720, 2020). "Once activated, KIT plays an important role in initiating the activation of MAPK/MEK and PI3K/AKT pathways that are critical in cancer development." (PMID 30847022, 2019).
cancer (continued). "Lessons learned from studying molecular mechanisms of resistance to ABL, EGFR, ALK, KIT, and RAF inhibitors in human cancers have highlighted the need for next-generation kinase inhibitors that are effective against acquired secondary resistance mutations." (PMID 31371345, 2019). "Imatinib inhibits the proliferation of cancer cells by suppressing the kinase activities of c-ABL, BCR-ABL, and c-KIT." (PMID 30344924, 2018). "Nilotinib binds to and inhibits the kinase domain of ABL/BCR-ABL but also interacts with other cancer-expressed kinases including DDR1, KIT and PDGFR." (PMID 27556570, 2016). "The effect of Imatinib on cancer cells including GBM has been mainly attributed to PDGFR inhibition, although it also targets ABL and KIT." (PMID 27732969, 2016). "Among them, several genes were related in cancer pathway such as EGFR, RARA, FGF2, FGFR1, FGFR2, FGFR3, KIT, and CCND1." (PMID 27016420, 2016). "For example, deregulated ABL is found in cancer cells with aberrant activation of RTKs, such as PDFGR, FGFR, EGFR, MET, KIT, and IGF1R." (PMID 27732969, 2016). "CFA 13 harbors several key cancer genes, most notably the c-MYC and c-KIT proto-oncogenes; however, CFA 13 gain manifests primarily as a whole chromosome aneuploidy, in contrast to the recurrent focal deletion of CFA 11q16." (PMID 25957863, 2015). "Among the 73 cancer amplified genes were a number of established drug targets, such as EGFR, ERBB2 and KIT." (PMID 24874471, 2014). "In human, this focal event contains a fragile site (FRA4B) and the well-known cancer genes PDGFR, KIT and KDR, which are also in the fish focal gain." (PMID 24009526, 2013). "KIT, CDH1, LSM7, C21orf4, DDI2 mRNA expression levels were significantly different between benign and malignant tumors, p(KIT) < 0.0001; p(CDH1) = 0.004; p(LSM7) = 0.03; p(C21orf4) = 0.01; p(DDI2) = 0.0001." (PMID 22958914, 2012). "Nielsen at al. determined that 13 of 21 basal-type cancers from microarray study were CK5/6-positive by immunohistochemistry, 12 of them were EGFR-positive, and 6 of them were c-KIT-positive." (PMID 20426817, 2010). "In addition to population-level changes, our studies identify signals such as KIT, thrombospondin, taurine and apolipoproteins from the TME that are essential for cancer progression." (PMID 40369079, 2025). "As a potent inhibitor of the RTK KIT, an oncogenic driver in about 80% of metastatic GIST, imatinib’s authorization also initiated a new era for the development of targeted therapies against cancers with molecularly defined driver alterations." (PMID 40018846, 2025). "Intriguingly, the high-throughput anti-cancer compound screening assays demonstrated that TFF3 inhibition by AMPC synergized most effectively with compounds targeting four distinct RTKs, EGFR, VEGFR, c-KIT, and c-MET in MDA-MB-361 and BT474 cells." (PMID 39920140, 2025). "It remains unknown whether ER stress signaling is essential for cell growth suppression/apoptosis in cancer cells expressing an RTK mutant, such as KIT in GISTs and EGFR in LAD." (PMID 38679330, 2024). "Ten tumors were negative for mutations in KIT, PDGFRA, and RAS-pathway genes (BRAF, RAS isoforms, and NF1), and for all other 161 cancer-relevant genes that were included in our NGS panel." (PMID 39199677, 2024). "Moreover, our analysis revealed cell-specific expressions, such as CARD11 in cancer cells, PNMA2 in proliferative cells, MAGEA3 in gland mucous cells, and KIT in chief cells." (PMID 38962317, 2024). "In WTs, POU2F3-positive cells tended to be on the abluminal side when two layers were recognizable and, at least partly, co-expressed p63 and p40, common abluminal markers, along with KIT and BCL2, which are often expressed in carcinomas with tuft cell-like phenotype." (PMID 38358561, 2024).
cancer (continued). "Notably, MYB, KIT, and FABP7 (the top-ranked signature genes) directly interact with NOTCH1, and these interactions have been reported to be involved in regulating cancer stem cell differentiation." (PMID 36879115, 2023). "As in addition to the classical NAB2-STAT6 fusion, we report four coding variants in cancer-associated genes (BIRC6, KIT, POLQ, and RBM10) which have not been previously reported in SFTs." (PMID 37469410, 2023). "Furthermore, 6r suppresses proliferation of cancer cells (GIST-T1 and HMC1.2) and c-KIT D816V Ba/F3 cells via blockade of c-KIT downstream signaling, and induction of apoptosis and cell cycle arrest." (PMID 36612139, 2022). "Molecular aberrations that were shared in at least one P/X pair and that were previously recognized to have deleterious effects in human cancers included CHEK2 [K416E; 415S (SNP)], EGFR (158N), ATM (P1054R), STK11 (D194N), PIK3CA (E545K), KIT (798I; M541L), and RUNX1 (L56S)." (PMID 34714554, 2022). "For example, targeting PI3K–Akt signal pathway to produce antileukemia effect is to use it to activate upstream oncogenes (such as Flt3–ITD, KIT, and NRAS), and calcium homeostasis disorder plays an important role in the pathogenesis of different kinds of malignant tumors." (PMID 36452344, 2022). "EGFR, KIT, MET, PPARG, and STAT5A were enriched in the Pathways in cancer, CAV1, EGFR, and MET were enriched in the Proteoglycans in cancer, and MET and PPARG were enriched in the Transcriptional misregulation in cancer." (PMID 35063044, 2022). "In cancers (not driven by c-KIT or Abl mutations), reducing mast cell numbers through c-KIT-targeting therapy alone has not yet proven to be a successful cancer strategy clinically or pre-clinically." (PMID 34063789, 2021). "KIT usually presents in multi-targeted TKIs as an inconspicuous target since a single selective KIT-TKI failed to cure most cancers." (PMID 33109256, 2020). "An array of mutations in splicing cis-acting sequences include those of LKB1 (liver kinase B1), KIT (v-kit Hardy-Zuckerman 4 feline sarcoma viral oncogene homolog), CDH17 (cadherin 17), KLF6 (Kruppel-like factor 6) and BRCA1 (breast cancer gene 1) in many types of cancers." (PMID 32905346, 2020). "Therefore, cancer‐related RTK become preferable targets for ADC development, e.g. RON, PTK7, FLT3, FGFR2, FGFR3, ERBB3, KIT and EPHA2." (PMID 31116512, 2019). "Similarly, in a previous study performed by the IMI using the AmpliSeq Cancer Panel HotSpot V2/CHPv2 on the Ion Torrent platform which investigates approximately 2800 mutations in 50 most common oncogenes and tumor suppressor genes, only KIT polymorphisms, but no mutations, were detected." (PMID 31455347, 2019). "According to several reports, KIT-positive cells in NB tumors (as opposed to AML) have cancer stem-like properties." (PMID 31681584, 2019). "Other RTK amplifications have also been reported in human cancers, including FGFR1 in lung and breast cancer, FGFR3 in breast and bladder cancer, ERBB4 in breast and gastric cancer, FLT3 in colon cancer, KIT in melanoma and GIST, and PDGFRA in GBM." (PMID 29455648, 2018). "We isolated SSEA4+ hSSCs and c-KIT+ spermatogonia from whole adult human testis, from five patients experiencing idiopathic pain, not involving cancer or major inflammation." (PMID 28985528, 2017). "Screening with OncoFOCUSTM+KIT has recently been introduced at the Flinders Centre for Innovation in Cancer (FCIC), an academic healthcare centre located in the southern suburbs of Adelaide that specialises in research and treatment of cancer." (PMID 28163892, 2016). "From the analysis of GBM dataset, we could find functional evidences of four targets including CDKN1A, MTAP, KIT and ATM among top 20 ranked miRNA-mRNA interaction pairs have been reported in GBM cancer." (PMID 25079112, 2014).
cancer (continued). "While other truncated tyrosine kinase receptors aberrantly expressed in cancer are constitutively active kinases, truncated c-KIT does not contain the ATP binding domain and should be catalytically inactive." (PMID 24709904, 2014). "Using the Taiwan Cancer Registry (TCR) data from 1998 to 2008, our analysis elucidated the incidence and the distribution of GISTs before and after the implementation of CD117 or KIT staining for the definitive diagnosis of GISTs and compared them to those in the Western countries." (PMID 24548660, 2014). "Among nine cancer-associated mutations that determine sensitivity to ATRA (Notch 1, BCR_ABL, KIT, FLT3, APC, TET2, K-ras, ALK, MLL_AFF1), KRAS, APC, and KIT mutations are associated with resistance to ATRA (only K-ras is shown)." (PMID 23982413, 2013). "This phenomenon is exemplified here for two private cases: PAX7, a homeodomain transcription factor that plays important roles during fetal development and cancer growth, and KITLG, a ligand of the KIT tyrosine-kinase receptor, which acts in cellular development." (PMID 22096567, 2011). "Even though deletions in chromosome 4 is a common feature in CRC, and known cancer genes such as KIT, EGF and FGF2 are situated here, none has yet been verified as predisposing for early onset or hereditary CRC." (PMID 20459617, 2010). "On the other hand, the invasive potential was not enhanced by SCF in the three KIT-negative cancer cell lines." (PMID 17044945, 2006). "By fluorescence in situ hybridisation, no KIT amplification was found in carcinomas with high KIT expression, but two cases showed a relative gain of chromosome 4." (PMID 15583695, 2004). "Furthermore, this type of cancer was found to rarely occur in extra-thoracic organs as biologically distinct subsets, which often exhibit poorly differentiated histology and overexpress the well-known oncogenes BCL2 and KIT." (PMID 37179317, 2023). "Additionally, prior assessment of relevant pharmacodynamic modulation in cancer cell lines demonstrated biochemical kinase selectivity (including inhibition of C-raf, wild-type B-raf, V599E mutant B-raf, VEGFR-2, c-KIT) for sorafenib at an IC50 ranging from 6 to 90 nM." (PMID 35664857, 2022). "Besides histological changes, expression of stem cells (OCT-4A, OCT-4, SSEA-1, SCA-1), early differentiation (c-KIT, MVH, Dmrt1a), Sertoli cells (SOX9), cancer stem cells (CD166), proliferation (PCNA, Ki67), global methylation (5mC) and tumor suppresser (PTEN)-specific markers were studied." (PMID 35676718, 2022). "Furthermore, several groups have reported differential expression of PKC isozymes by cancer type, for example, PKCθ overexpression in KIT-negative GISTs or PKCα overexpression in OTSCC." (PMID 36358843, 2022). "Notably, TIE1, KIT, NTRK1, FGFR3, CSF1R, and INSRR were shared by both cancers." (PMID 34944663, 2021). "Although there have been few reports of KIT being regulated epigenetically, in vitro studies have indicated that cancer cell lines that tends to overexpress the KIT gene are often more aggressive, while cell lines that lacked KIT expression were hypermethylated for this gene." (PMID 24626295, 2014). "This has been shown with a truncated isoform of KIT (tr-KIT) and a truncated isoform of VEGFR-1 (i21-VEGFR-1), which are intracellular and require no ligand binding, but are nonetheless able to activate Src and induce cell migration and invasion of cancer cells." (PMID 24709904, 2014). "Furthermore, with exception of GISTs, the presence of overexpression of KIT and PDGFRA in human cancers was not correlated with presence of activating mutations." (PMID 23497641, 2013).
cancer (continued). "KIT/PDGFRA inhibitors such as imatinib mesylate are the mainstay of medical treatment for advanced GIST but they are not curative due in part to secondary mutations interfering with drug action or lack of dependence of cancer-initiating cells on KIT/PDGFRA signaling." (PMID 24116170, 2013). "Thus, we anticipate that masitinib will be effective for the treatment of KIT and PDGFR-dependent diseases, which include various cancer and inflammatory diseases, and that it will have a better safety profile, especially regarding cardiotoxicity, than other KIT inhibitors." (PMID 19789626, 2009). "On the other hand, SCF did not enhance proliferation of KIT-negative cancer cell lines." (PMID 17044945, 2006). "Previous studies revealed that overexpression of receptor tyrosine kinases such as c-KIT and platelet-derived growth factor receptor (PDGFR), which show a very high structural similarity and almost identical mechanisms of action, may play an important role in the development of this cancer." (PMID 40076604, 2025). "The implementation of the National Genomic Test Directory for Cancer in England and access for all patients to NGS panels may provide greater information on the incidence of non-BRAF-V600E mutations, as well as data for NRAS and KIT." (PMID 40902091, 2025). "Finally, the effect of the recent development of KIT/PDGFRA inhibitors is ripretinib (formerly DCC-2618), whose effectiveness in inhibition of a wide range of KIT mutants in patients with drug-resistant GISTs has been confirmed in preclinical cancer models and preliminary clinical data." (PMID 36291774, 2022). "However, the intersection of immunology and cancer biology creates challenges whereby a single genomic driver or biomarker (for example BRAF, KIT, or EGFR mutations in targeted therapies) do not adequately explain or predict response among patients being treated with anti-PD1 therapies." (PMID 32708981, 2020). "While KIT mutations are well-known drivers of GIST, tissue-specific genes such as the serine/threonine protein kinase TESK1, the myelin regulatory factor MYRF, as well as the 5-oxo-L-prolinase OPLAH or the zinc influx transporter SLC39A9 have not been associated with cancer before." (PMID 26102504, 2015). "Similarly to KIT, PDGFRA and their ligands, insulin-like growth factor (IGF)-1 receptor (IGF1R), a type 2 RTK, and its ligands IGF1 and IGF2 play critical roles in normal growth and development, as well as in cellular stress, aging and cancer by stimulating protein synthesis and the cell cycle." (PMID 24116170, 2013). "In the 78 CNS tumors with histologies not included in prior pediatric pan-cancer analyses, the recurrently altered genes uniquely containing oncogenic alterations (compared to the common tumors) were CTNNB1, NF2 and KIT." (PMID 38992034, 2024). "VGFR1, KIT, FGFR1 and RET were expressed at similar levels in healthy and non-tumorous (histologically normal) livers from cancer patients." (PMID 36890818, 2023). "Further, we found six genes—FOXL2, TNFAIP3, CHD1L, HRAS, KIT, CTCF—that occurred in 12 cases that are not on the top 20 list of any of the four common cancers used for comparison." (PMID 32570879, 2020). "Most slides from cancer-free tissue lacked expression of CCND1, CD44, CDH1, EGFR, ERBB2, KIT, keratins, NOTCH1, PAK1, PTGS2, SNAI1, and VIM but showed staining of MUC1, HIF1A, NKX2-1, SFTPC, and STAT3, which were also found in AdCa." (PMID 23028920, 2012). "CD117 (c-KIT), CD56, and CD133 were negative in both sarcomatoid and carcinoma components." (PMID 29504997, 2018). "PC1 cancer cells had no c-KIT protein expression, and PC2 cells showed very weak c-KIT expression." (PMID 29207991, 2017). "Because KIT and BCL2 are often highly expressed in POU2F3-positive tuft cell-like carcinomas, the same feature in WTs could suggest that non-neoplastic POU2F3-positive cells might express BCL2 and KIT via non-mutational, possibly epigenetic mechanisms that, in turn, might be smoking-related." (PMID 38358561, 2024).
cancer (continued). "Additionally, some outliers may represent cancer lineage markers or non-cancer cells within tumors and not necessarily a somatically altered pathway, such as the 58% of KICH expressing KIT." (PMID 30053901, 2018).